FGF21 (fibroblast growth factor 21)
Diseases named in the same sentence as FGF21 in open-access papers (continued):
Sharing a sentence is not in itself a finding about the gene and the disease.
Obesity (continued). "How then, should “FGF21 resistance” during obesity be defined?" (PMID 29983922, 2018). "One‐time administration of these vectors to obese animals enabled a long‐lasting increase in FGF21 levels in circulation, which resulted in sustained counteraction of obesity, adipose tissue inflammation, insulin resistance, and NASH in the absence of adverse events." (PMID 29987000, 2018). "Obesity distinctly increased plasma FGF-21 (chow ad libitum vs. HFD ad libitum), which showed a trend toward higher concentrations under exposure to hypoxia than under food restriction (pmol/l: hypoxia, 44.1 ± 9.5, vs. weight matched control, 23.7 ± 3.6; p = 0.058)." (PMID 30210452, 2018). "A recent study suggested a beneficial effect of mTOR by mediating the anti-obesity effects of fibroblast growth factor 21 (FGF21), implying complex pathways linking obesity and ageing which may involve negative feedback mechanisms." (PMID 28957990, 2018). "Continuous cerebral administration of FGF-21 for 2 weeks increased whole body insulin sensitivity in rats with dietary-induced obesity, whilst daily intravenous or subcutaneous delivery of FGF-21 for 6 weeks improved glucose handling in diabetic rhesus monkeys." (PMID 29760587, 2018). "It is possible that increased circulating FGF21 during obesity could serve a yet uncharacterized role." (PMID 29983922, 2018). "Activation of KLB/FGFR1c by native or synthetic FGF21 molecules has been shown to induce body weight loss and reduce circulating triglyceride levels in rodent models of obesity, non-human primates and humans." (PMID 30106981, 2018). "Moreover, it was suggested that FGF21 corrects obesity in mice partly by promoting futile cycling in adipose tissue." (PMID 30275870, 2018). "Presence of FGF-21 resistance in obesity has indeed been demonstrated in animal models." (PMID 30298107, 2018). "The study of FGF21 in individuals with ISO and insulin-resistant overweight and obesity (IRO) can help us to understand whether FGF21 is involved in the protection from the progression to insulin resistance in the development of obesity." (PMID 29348470, 2018). "However, obesity is characterized by FGF21 resistance, increased level of FGF21, and decreased expression of β-Klotho in adipose tissue and liver." (PMID 30671457, 2018). "These suggest that Sp1 may be responsible for the elevated FGF21 expression in adipose tissue of diet-induced obesity mice." (PMID 28466020, 2017). "In addition, the results raise concern for the proposed use of FGF-21 as pharmacologic treatment in obesity until physiological actions are further clarified." (PMID 28694840, 2017). "Given that Sp1 positively regulates FGF21 basal transcriptional activity in HepG2 cells and 3T3-L1 cells, we investigated whether Sp1 has a direct effect on the upregulation of FGF21 transcription in HFD-induced obesity mice model." (PMID 28466020, 2017). "Brown adipose tissue activity has been associated with non-shivering thermogenesis in mammals and Fgf-21 secretion, which improves glycaemia and lipidaemia preventing some aspects of obesity and metabolic diseases." (PMID 28319140, 2017). "FGF21 is paradoxically increased in obesity, suggesting that obesity is a FGF21-resistant state." (PMID 28780756, 2017). "Based on our profiling data, we hypothesized that maintaining adipose KLB expression during diet-induced obesity would sensitize mice to endogenous, circulating FGF21, thus preventing FGF21 resistance and potentially improving insulin sensitivity." (PMID 28580290, 2017). "Furthermore, we identified Sp1 contributes to the obesity-induced FGF21 upregulation in mouse adipose tissue and hepatic FGF21 upregulation in hepatocarcinogenesis." (PMID 28466020, 2017). "For example, plasma FGF21 levels are elevated in both rodents and humans in response to high carbohydrate levels, protein restriction, fasting, and obesity and insulin resistance." (PMID 28580290, 2017).
Obesity (continued). "Therefore, the potential combined use of exercise and FGF21 as therapy for chronic metabolic diseases such as obesity, diabetes, and the metabolic syndrome deserves further examination." (PMID 28801668, 2017). "This means that obesity itself may regulate not only insulin sensitivity, but also the serum FGF21 levels." (PMID 28582462, 2017). "However, obesity is thought to be an FGF21-resistant state because of the elevated endogenous FGF21 levels." (PMID 28770320, 2017). "Previous work has suggested that impairment of FGF21 signaling in adipose tissue may occur through downregulation of the obligate FGF21 co-receptor, β-klotho, which leads to “FGF21 resistance” during the onset of diet-induced obesity." (PMID 28580290, 2017). "Obesity and diabetes are known for increasing circulating FGF21 levels." (PMID 28770320, 2017). "Some studies reported that increasing of FGF21 could ameliorate obesity and diabetes through enhancing glucose uptake, suppressing adipogenesis, or increasing lipolysis both in vitro and in vivo." (PMID 29109955, 2017). "In this study we examined whether the marked reduction in β-klotho levels in white adipose tissue observed during obesity contributes to impaired FGF21 sensitivity in vivo." (PMID 28580290, 2017). "However, it has also been suggested that obesity is an FGF21-resistant state in the context of effects of endogenous levels of FGF21, indicating the lack of a benefit by FGF21 exposure in obese models." (PMID 28770320, 2017). "In addition, circulating FGF21 was also increased in several pathological statuses including obesity, diabetes, and other metabolic syndromes in rodents and humans." (PMID 29109955, 2017). "In this context, our findings suggest that obesity comprises a state of FGF-21 resistance." (PMID 28694840, 2017). "Furthermore, we demonstrated that Sp1 contributes to the obesity-induced FGF21 upregulation in mouse adipose tissue and hepatic FGF21 upregulation in hepatocarcinogenesis." (PMID 28466020, 2017). "In addition, in relation to normal lean individuals, FGF21 was up to 2.0-fold higher in people with obesity and type 2 diabetes." (PMID 28770320, 2017). "To test whether directly improving hepatic insulin sensitivity and glucose homeostasis in the background of HFD-induced obesity could lead to a reduction in FGF21 levels, we examined mice with a hepatocyte-specific knock-out of PTP1B." (PMID 28256636, 2017). "Serum FGF21 levels could also be induced by other clinical conditions such as fasting, obesity, liver injury, cirrhosis, renal dysfunction, metabolic syndrome, type 2 diabetes and coronary disease." (PMID 27358750, 2016). "FGF21 positively affects the metabolic profile of mice with diet-induced obesity." (PMID 27057099, 2016). "FGF21 alleviates endoplasmic reticulum stress or obesity-induced hepatic steatosis." (PMID 28025491, 2016). "The present study attempts to determine whether metformin functions as a treatment for obesity by inducing the expression of FGF21." (PMID 27057099, 2016). "Therefore, our study suggests that CB1 receptor-induced ERRγ contributes to the FGF21-mediated compensatory mechanism to oppose CB1 receptor-mediated diet-induced obesity." (PMID 27455076, 2016). "The relationship between FGF21 and obesity remains controversial." (PMID 27190511, 2016). "However, high circulating FGF21 levels are found in obesity and it is related to cardio-metabolic disorders including the MS, type 2 diabetes, NAFLD and coronary artery disease in human studies." (PMID 27471739, 2016). "Overexpression of FGF21 in transgenic mice prohibits diet-induced obesity." (PMID 27798284, 2016). "The multiple beneficial effects of FGF21 on glucose and lipid metabolism and insulin sensitivity suggest that it might represent a promising therapeutic agent to treat diabetes and other obesity-related metabolic disorders." (PMID 27471739, 2016).
Obesity (continued). "Thus, FGF21 is emerging as a promising therapeutic for treating type 2 diabetes and the metabolic syndrome related to obesity." (PMID 27409675, 2016). "Since its initial identification, fibroblast growth factor 21 (FGF21) has been shown to be a key hormonal regulator of glucose metabolism and energy balance, representing a promising potential approach for the treatment of obesity and T2DM." (PMID 27405817, 2016). "These newly observed physiological functions are exerted via actions on the SNS and via FGF-21-mediated humoral control, and may explain the previously reported anti-obesity effects of GALP." (PMID 26892462, 2016). "Hence, FGF-21 has emerged as a promising treatment for obesity, type 2 diabetes, and liver diseases." (PMID 26790818, 2016). "While metabolic profiles are drastically improved by FGF21 in obese rodent models, the results considerably differ among species, thus questioning the appropriateness of FGF21 for the treatment of human diseases, such as obesity, hyperlipidemia, and type 2 diabetes." (PMID 26441837, 2015). "Although whether or how Fgf21 might affect peroxisome proliferation requires further studies, these effects point to the induction of Fgf21 as a potential therapeutic strategy against obesity and dyslipidemia." (PMID 25659146, 2015). "FGF-21 transgenic mice were resistant to high-fat diet-induced obesity and their BAT was denser." (PMID 26441838, 2015). "Furthermore, pre-clinical studies revealed that FGF21 administration leads to improvement in the metabolic consequences of obesity, such as dyslipidemia and type 2 diabetes." (PMID 25985218, 2015). "Furthermore, in an ischemia animal model, FGF21 was found to exert a cardioprotective effect, which was diminished in obesity." (PMID 26091256, 2015). "In adults, the circulating levels of FGF21 increase under adverse lipid profiles, obesity, metabolic syndrome, impaired glucose tolerance, type 2 diabetes mellitus, or atherosclerosis, but in children its relationship with metabolic syndrome has not been confirmed." (PMID 26379757, 2015). "In addition, FGF21 alleviates the major risk factors of NAFLD, including obesity, dyslipidemia, and insulin insensitivity." (PMID 26441837, 2015). "FGF21 reverses hepatic steatosis, counteracts obesity, and improves insulin insensitivity." (PMID 26441837, 2015). "Furthermore, Chau demonstrated that FGF21 was a potential function as a therapy for obesity by activating AMPK-sirtuin 1 (SIRT1)-PGC-1α pathway." (PMID 26703591, 2015). "Interestingly, in children levels of FGF-21 showed a parallel increase with the grade of hepatic fat content independently of obesity development, visceral fat, and either hepatic or adipocyte IR." (PMID 25356508, 2014). "Taken together, these findings demonstrate that FGF21 plays an important role in the regulation of glucose and lipid metabolism and also suggest that FGF21 exhibits the therapeutic characteristic necessary for the effective treatment of diabetes and obesity." (PMID 24895642, 2014). "Since Fgf21 plays an important role in regulating energy balance, obesity and body weight in mammals, we speculate that this gene may also play a role in glucose and lipid metabolisms, and even in controlling growth and body weight in fish." (PMID 24587261, 2014). "The increase in circulating Fgf21 induced by liraglutide might therefore contribute to the improvement of obesity and hyperglycemia in individually housed KKAy mice." (PMID 24804243, 2014). "Furthermore, the effects of FGF21 on the attenuation of obesity-induced impairments in insulin signaling in the liver and skeletal muscle are abrogated in adiponectin knockout mice." (PMID 24605108, 2014). "Both βKlotho (an essential co-factor for FGF21 signalling) mRNA (data not shown) and protein levels was significantly decreased in obese hearts [P<0.05 vs.lean; Figure 5C1], further supporting the concept of decreased FGF21/FGF-R1/βKlotho signalling in obesity." (PMID 24498293, 2014).
Obesity (continued). "The deficiency in autophagy and subsequent mitochondrial dysfunction could promote FGF21 expression, which in turn protects from diet-induced obesity and insulin resistance." (PMID 25295245, 2014). "In relation to this, the concept of ‘FGF21 resistance’ in obesity has been proposed." (PMID 24498293, 2014). "Fgf21 transgenic mice are resistant to diet-induced obesity." (PMID 24605108, 2014). "Paradoxically, FGF21 levels are elevated in obesity and obese mice treated with recombinant FGF21 have a blunted metabolic response to FGF21, which suggests that resistance to the actions of FGF21 may develop in obesity." (PMID 24205333, 2013). "In humans, circulating FGF-21 is increased in obesity and in subjects with type 2 diabetes." (PMID 23533568, 2013). "Intriguingly, it was recently shown that FGF21 expression is increased in skeletal muscle of muscle-specific Akt1 transgenic mice which exhibit protection from high-fat diet (HFD)-induced obesity and insulin resistance, indicating the beneficial effects of FGF21 as a myokine in metabolic disorders." (PMID 23667629, 2013). "FGF21 is a crucial mediator in the adaptive metabolic response to starvation, and is an excellent therapeutic molecule for treatment of type 2 diabetes and obesity in rodents and monkeys." (PMID 23667629, 2013). "They suggested fibroblast growth factor 21 (FGF21) to protect Nrf2 KO mice from obesity." (PMID 24194976, 2013). "However, in response to fasting and starvation, a ketogenic diet, NAFLD, steatosis, obesity and type 2 diabetes, the expression of FGF21 is increased significantly." (PMID 23590285, 2013). "Furthermore, in diet-induced obesity in mice, FGF-21 is enhancing insulin-mediated suppression of endogenous glucose production and enhancing insulin-mediated glucose uptake in skeletal muscle." (PMID 23533568, 2013). "Pre-clinical studies in animal models for obesity demonstrated that low doses of K-877 (0.3-3.0 mg/kg) had a greater TG-lowering efficacy than 1,000-fold higher doses (300 mg/kg) of fenofibrate, an effect that was accompanied by higher levels of plasma FGF-21." (PMID 23721199, 2013). "Similarly, in rodents, plasma FGF21 is increased in animal models of obesity and type 2 diabetes (e.g., ob/ob mice), but also in response to prolonged fasting in mice." (PMID 23118742, 2012). "In addition to starvation, an increase in hepatic FGF21 generally accompanies hepatic stress-inducing conditions of obesity and chemical insult, infection and inflammation." (PMID 23106963, 2012). "Because FGF21 resistance might be found in obesity and in renal failure, leading to compensatory upregulation of this hepatokine." (PMID 21525989, 2011). "In addition, FGF21 stimulates glucose uptake in adipocytes and protects from diet-induced obesity and metabolic disorders in obese or diabetic animals given FGF21 and in FGF21 transgenic mice." (PMID 21829679, 2011). "Furthermore, mice overexpressing FGF-21 was resistant to diet-induced obesity and exhibited improved glucose homeostasis." (PMID 22046277, 2011). "In addition, it had been demonstrated that plasma FGF-21 levels were elevated in insulin-resistant states (obesity, IGT/IFG, T2DM) and were inversely correlated with both peripheral and hepatic insulin sensitivity." (PMID 22046277, 2011). "However, FGF-21 levels are paradoxically higher in obesity, indicating a hormone-resistant state that may hinder the benefits of SGLT2i." (PMID 40059147, 2025). "Recent data suggest intermittent fasting may affect obesity-induced FGF-21 resistance." (PMID 40430125, 2025). "This review synthesizes evidence linking GDF15 to obesity, diabetes, cardiovascular diseases, metabolic liver disorders, cachexia, sarcopenia, and aging while exploring its interactions with key metabolic factors including FGF21, GLP-1, leptin, and glucocorticoids." (PMID 40837873, 2025).
Obesity (continued). "Therefore, the metabolic stress imposed by fasting and refeeding may activate protective pathways, such as FGF21 secretion, which could be particularly beneficial for individuals with metabolic disorders, including obesity and metabolic syndrome." (PMID 41117265, 2025). "Additionally, heightened FGF21 expression in skeletal muscle plays a role in shielding against diet‐induced obesity and IR,623, 624 indicating that muscle‐derived FGF21 could be a regulator of integrated energy and lipid metabolism." (PMID 39764565, 2025). "Therefore, the purpose of this study was to assess the relations between both serum FGF-21 and Visfatin with the obesity and its metabolic disorders, and their use as potential predictors for metabolic risk factors in a sample of Egyptian obese and non-obese children." (PMID 38216702, 2024). "Notably, in mice lacking adiponectin, the beneficial effects of FGF21, such as alleviating obesity-associated insulin resistance, hyperglycemia, hyperlipidemia, and hepatic steatosis, are diminished." (PMID 39408777, 2024). "Moreover, obesity induced by a high-fat diet alters the M1/M2 macrophage ratio and promotes tumor fibrosis through the upregulation of fibroblast growth factor 21 (FGF21), thereby diminishing the efficacy of standard chemotherapy treatments such as paclitaxel and carboplatin in murine models." (PMID 38540217, 2024). "Thus, the molecular mechanisms of FGF21 resistance in obesity and metabolic disorders remain unclear." (PMID 39211324, 2024). "FGF21 may have the potential to treat diabetes and obesity by acting on the CNS." (PMID 39062868, 2024). "Moreover, FGF21 intervention in diet-induced obesity and ob/ob mice resulted in energy expenditure changes, enhanced fat oxidation, and the inhibition of liver new fat production, thus improving the obesity phenotype." (PMID 37576954, 2023). "We propose FGF21 as a marker able to differentiate metabolic health in children with normal weight, while leptin could be used to detect unfavorable metabolic profiles under states of already established obesity." (PMID 38138907, 2023). "Cytokeratin-18 fragment plasma levels above 150 U/L may reflect even mild liver injury and involve metabolic complications of obesity, especially insulin resistance, disturbed lipid postprandial metabolism, low-grade inflammation and inefficient FGF21 signaling." (PMID 37189422, 2023). "Therefore, some researchers have questioned whether FGF21 resistance exists in patients with obesity and other related metabolic diseases." (PMID 37424900, 2023). "To date, several studies identified FGF-21 as an important player in the pathogenesis of various cardiovascular and metabolic diseases, such as atherosclerosis, coronary heart disease, myocardial infarction, obesity or non-alcoholic fatty liver disease (NAFLD)." (PMID 37239098, 2023). "Therefore, on the one hand a possible resistance to beneficial FGF-21-mediated effects in states of metabolic disorders, such as obesity or T2D, and on the other hand a reactive increase to overcome the increased energy income and triglyceride (TG) accumulation is discussed." (PMID 37239098, 2023). "Currently, several studies have shown that FGF21 may be a potential target for obesity treatment." (PMID 37576954, 2023). "Resistance to FGF21 is hypothesized to be a component of obesity-related endocrine changes." (PMID 37712012, 2023). "Therefore, FGF-21 is considered to have a novel therapeutic potential for obesity, T2DM, and NAFLD." (PMID 37436597, 2023). "Consequently, only VAT seems to be implied in FGF-21-regulated pathways in obesity." (PMID 37409233, 2023). "To explore whether liver-derived FGF21 is involved in OVX-induced body weight gain and obesity in females, we bilaterally ovariectomized FGF21 LKO and their wild-type (WT) littermates at 6 weeks of age and then monitored their body weight change weekly until the age of 30 weeks." (PMID 37834368, 2023).